YY1 (YY1 transcription factor)
Diseases named in the same sentence as YY1 in open-access papers (continued):
Sharing a sentence is not in itself a finding about the gene and the disease.
tumor (continued). "In summary, YY1 drives tumor cell resistance by promoting DNA damage repair." (PMID 40867514, 2025). "This widespread overexpression across diverse cancer types supports the hypothesis of YY1 playing fundamental roles in tumor biology, particularly in promoting proliferation and survival pathways." (PMID 41009346, 2025). "Altogether, these results support the hypothesis that YY1 is overexpressed in malignant breast tissue and plays a potential role in tumorigenesis and tumor progression." (PMID 41009346, 2025). "Thus, while YY1 actively drives tumor growth through oncogenic signaling, RKIP counters these effects by silencing survival pathways and limiting autophagic support." (PMID 41327312, 2025). "This indicates that MRPL42 acts as an oncogene in LUAD, with its expression regulated by YY1.The expression of MRPL19 is upregulated in LUAD and is associated with lymph node metastasis, tumor differentiation, and pathological status, indicating poor prognosis." (PMID 40371222, 2025). "Most clinical characteristics were not related to YY1 expression; however, we found that a larger tumor size, a feature with an elevated risk of spread, was significantly associated with a high YY1 value (57.7 vs. 44.2%, p = 0.037)." (PMID 41009346, 2025). "Given MAGEA6's role in tumor migration and invasion, we investigated whether YY1 contributes to these processes." (PMID 40145793, 2025). "Similarly, YY1 has been shown to regulate various tumor suppressors depending on the type of cancer involved." (PMID 41327312, 2025). "Moreover, recent studies have demonstrated competitive binding between YY2 and YY1 to identical DNA binding sites, leading to antagonistic regulation of ferroptosis in tumor cells." (PMID 41235100, 2025). "Accordingly, YY1 prognostic behavior changes according to the tumor type." (PMID 39796650, 2024). "We found that overexpression of YY1 promoted tumor progression in vivo." (PMID 38347631, 2024). "Thus, many studies have confirmed that YY1 and non-coding RNAs are involved in a complex crosstalk that influences tumor progression." (PMID 38339244, 2024). "However, more research is needed to understand the role that each of these different amino acid motifs play in the function of YY1’s role in its different pleiotropic anti-tumor activities." (PMID 39796650, 2024). "Notably, tumor growth was markedly inhibited when both of KDM5C and YY1 were depleted, whereas the loss of either KDM5C or YY1 only negligibly influenced ACHN cell growth." (PMID 39433896, 2024). "However, further research is needed to develop tumor-cell-specific Inh-YY1, possibly through the use of Inh-YY1–antibody conjugates and nanotechnologies, for clinical applications." (PMID 38539569, 2024). "In addition, YY1 also regulates PD-L1 expression in tumor cells, cell proliferation, metastasis, and resistance to therapeutics." (PMID 39796650, 2024). "Nitric oxide (NO) donors, like DETA/NO, have also shown the capability to enhance RKIP expression by inhibiting the NF-κB/YY1/Snail regulatory circuit, leading to heightened sensitivity to tumor chemo-immuno-sensitization and the inhibition of EMT and metastasis." (PMID 38786085, 2024). "Furthermore, simultaneously targeting KDM5C and YY1 effectively inhibited tumor growth in KDM5C-proficient tumor cells." (PMID 39433896, 2024). "In addition, YY1 regulates PD-L1 on tumor cells and is intimately involved in the pathogenesis of tumor cells." (PMID 39796650, 2024). "Further, YY1 regulation of PD-1 is tied to tumor-infiltrating lymphocyte exhaustion." (PMID 38539569, 2024). "Furthermore, studies focused on cervical cancer cases found that miR-181 negatively regulates YY1 expression and additionally inhibits tumor cell proliferation." (PMID 38539569, 2024).
tumor (continued). "We hypothesized that the inhibition of LAG-3 expression, by inhibiting its regulation by YY1, offers an alternative to CPIs that could lead to the restoration of the anti-tumor CD8 T cell function and be effective in cases of resistance to CPIs." (PMID 39796650, 2024). "Hence, targeting YY1 in CD8 T cells will result in restoring the anti-tumor immune response and tumor regression." (PMID 39796650, 2024). "Thus, targeting YY1 will have a multitude of anti-tumor activities resulting in a significant obliteration of cancer oncogenic activities." (PMID 38539569, 2024). "Importantly, we found that OTUD3 acts as an oncogene to accelerate CRC tumor growth by enhancing YY1 stability while YY1 depletion reversed OTUD3 overexpression-induced tumor progression." (PMID 38351178, 2024). "Additionally, compared to adjacent normal tissues, the tumor tissues exhibited significantly higher YY1 expression." (PMID 38347631, 2024). "Interestingly, YY1 displays a dual function in transcriptional regulation and tumor growth, functioning both as an activator and a suppressor." (PMID 38347631, 2024). "Notably, YY1 exhibited significantly elevated expression in tumor tissues compared to adjacent normal tissues." (PMID 38347631, 2024). "Due to YY1’s role in tumor progression and development, its inhibition may promote apoptosis and chemo-response, enhance immune CD8+ T-cell activity, and block tumor growth." (PMID 38539569, 2024). "However, in the context of an immune suppressive tumor microenvironment, YY1 regulates the proliferation and function of Tregs through remodeling of the Foxp3 locus." (PMID 38339244, 2024). "They showed that YY1 is clearly critical for the tumor-immune microenvironment." (PMID 39796650, 2024). "Importantly, targeting YY1 effectively inhibited the proliferation and tumorigenicity of tumor cells with low KDM5C expression." (PMID 39433896, 2024). "Drug delivery to the tumor site is another challenge of targeting YY1." (PMID 39796650, 2024). "Targeting YY1 directly on CD8 T cells or tumor cells remains the main challenge." (PMID 39796650, 2024). "In addition, both NRP1 and YY1 are involved in the adaptation of tumor cells to hypoxia, a condition commonly observed in tumor microenvironment due to rapid consumption of oxygen for rapid proliferation and high metabolism." (PMID 38672608, 2024). "Our results confirmed that OTUD3 facilitated tumor growth by up-regulating YY1." (PMID 38351178, 2024). "Another approach to reduce YY1 mRNA and target tumor angiogenesis could be the use of RNA interference." (PMID 38339244, 2024). "Hence, YY1 has countless different roles in both the upregulation of certain oncogenes and the suppressing of different tumor suppressor genes." (PMID 39796650, 2024). "In this regard, it is tempting to speculate that targeting tumor YY1 may normalize tumor perfusion, favoring the recruitment of effector T cells and antitumoral immunotherapy." (PMID 38339244, 2024). "The pro-tumor effect of YY1 in GBM process has been confirmed." (PMID 38410123, 2024). "Additionally, the protein synthesis inhibitor anisomycin also was found to induce cuproptosis in tumor cells, likely via inhibiting Yin Yang 1 (YY1)-mediated transcriptional activation of the key genes in the LA pathway (i.e., FDX1, DLD, DLAT, and PDHB)." (PMID 38918694, 2024). "The OTUD3 and YY1 protein expression levels were positively correlated in the tumor samples." (PMID 38351178, 2024). "For example, in tumor cells, using a nitric oxide donor showed that the drug not only inhibited YY1 expression, but also caused cytokine release syndrome." (PMID 39796650, 2024). "Thus, this pathway stimulates PD-1 upregulation via increased YY1 expression, leading to the exhaustion of tumor-infiltrating T lymphocytes and cancer progression." (PMID 38539569, 2024).
tumor (continued). "Although inhibitors of YY1 have not yet been approved for clinical use in GBM treatment, it is important to note that targeting YY1 could disrupt the signaling pathways that contribute to tumor growth and survival." (PMID 38893192, 2024). "These two facets of YY1, tumor growth promotion versus suppression, remain unclear and further research is needed for the elucidation of prognostic implications." (PMID 37444605, 2023). "YY1 overexpression was found to be significantly associated with a better prognosis, and YY1 expression functioned as a favorable prognostic factor after adjustment of HR/HER2 status and tumor size." (PMID 37444605, 2023). "Furthermore, the reduction in NE marker expression, inhibition of NCI‐H660 cell proliferation, and suppression of subcutaneous tumour growth in vitro and in vivo were observed upon YY1 knockout in NCI‐H660 (NEPC cells)." (PMID 37771187, 2023). "Further evidence for this series of oncogenic events came from the fortuitous capture of tumour-associated TAL2/3 cells that displayed a pre-transformed state retaining TFCP2L1 activity, while at the same time showing MYC and YY1 activity accompanied by a hypoxia and stress signature." (PMID 37236926, 2023). "As a transcription factor (TF), YY1 both activates and suppresses the expression of a number of oncogenes and tumor suppressors involved in various cellular functions, including proliferation, angiogenesis, metastasis, DNA damage response, redox homeostasis, apoptosis, and immunosuppression." (PMID 37444605, 2023). "This analysis revealed the presence of a well-known tumor inducer, Yin Yang 1 (YY-1)." (PMID 37495623, 2023). "In consequence, changes in zinc levels may affect YY1’s activity in various ways, leading to alterations in gene expression patterns and potentially resulting in neoplastic transformation or tumor progression." (PMID 37686614, 2023). "YY1 plays a dual role in both suppressing and promoting tumor growth." (PMID 37686541, 2023). "Thus, we demonstrated that CENPA interacts with YY1, forming the transcriptional complex, to co-regulate a set of genes involved in tumor progression." (PMID 37928273, 2023). "The tumor microenvironment plays a crucial role in tumor progression and the treatment response and could impact the efficacy of YY1-targeted therapies in multiple ways." (PMID 37444616, 2023). "YY1, through several distinct mechanisms, promotes the proliferation of glioma tumor cells." (PMID 37568827, 2023). "Conversely, the YY1 suppression significantly impeded tumour growth." (PMID 37771187, 2023). "YY1 could also promote the survival of tumor cells in the presence of chemotherapy drugs by repressing anti-apoptotic genes such as Bcl2-interacting mediator of cell death (Bim) and increasing protein B-cell lymphoma-extra-large (BCL-xL)." (PMID 37444616, 2023). "In cancer cells, YY1 has the ability to promote and repress tumor growth." (PMID 37686541, 2023). "Hence, these results strongly suggest that YY1 is critically important for the tumor immune microenvironment." (PMID 37081988, 2023). "In addition, YY1 can promote tumor cell invasion and metastasis by regulating expression of the genes involved in cell adhesion and migration." (PMID 37444616, 2023). "Additionally, YY1 siRNA and the chemical inhibitor Kenpaullone result in tumor cell sensitization to drug-induced apoptosis." (PMID 37686541, 2023). "Moreover, animal studies have also shown that treatment with DETA-NONOate in combination with cisplatin led to a significant reduction in the expression levels of YY1 and Bcl-xL in tumor tissues." (PMID 37444616, 2023). "Results showed that ISO may also change the tumor immune microenvironment by reducing the level of YY1 and enhance the immune killing ability of T-cells." (PMID 37408047, 2023). "A subcutaneous injection model was used to examine YY1 involvement in tumour growth in vivo." (PMID 37771187, 2023).
tumor (continued). "Therefore, YY1 can serve as a tumor marker for diagnosis and prognosis, and it can be an effective target for antitumor chemotherapy and immunotherapy." (PMID 37408047, 2023). "Although many YY1‐repressed genes exhibit tumor suppressive potential, YY1 silencing may lead to chemotherapy resistance." (PMID 36880159, 2023). "In addition, we discussed the potential value of YY1 in tumor diagnosis and treatment and provided a novel molecular strategy for the clinical diagnosis and treatment of tumors." (PMID 37081988, 2023). "CTCF, FOS, ATF2, and YY1 in H3F3B+ tumor cells were found to regulate angiogenesis." (PMID 37430270, 2023). "YY1BM specifically binds to the transcription factor YY1, blocking its interaction with the androgen receptor (AR) and leading to the downregulation of eukaryotic elongation factor 2 kinase (eEF2K) expression in tumor cells through the AR signaling pathway." (PMID 37444616, 2023). "Previous studies showed that YY1 promotes cancer and tumor development in humans." (PMID 37623635, 2023). "For example, studies investigating the effects of YY1 inhibition in tumor cells using a nitric oxide donor found that the drug not only inhibited YY1 expression but also caused cytokine release syndrome." (PMID 37444616, 2023). "In addition, in the studies evaluated for all paired primary and metastatic samples, YY1 expression appeared to be increased in metastatic tissues compared with matched primary tumor tissues." (PMID 37081988, 2023). "Moreover, patients with lower expression of KIF3B correlated with fewer residual tumor and better survival rate, thus indicating YY1 influenced the radiosensitivity of ESCC through regulation of KIF3B." (PMID 38065955, 2023). "YY1 may indirectly participate in reprogramming glucose metabolism in tumor cells by promoting the stability of HIF-1α under hypoxic conditions to enhance GLUT1 and GLUT3 expression." (PMID 37081988, 2023). "Several previous studies have reported that YY1 plays a tumor suppressor role in PCDA." (PMID 37081988, 2023). "Besides histone modifications, YY1 can be targeted directly or indirectly by a variety of non‐coding RNAs (ncRNAs) that act as tumor suppressors." (PMID 36880159, 2023). "Consistently, knockdown of RP11-367G18.1 variant 2 or YY1 suppressed the tumor growth of xenografted FADU cells overexpressing HIF-1α (ΔODD), suggesting that hypoxia-induced tumorigenicity was attributable to the RP11-367G18.1 variant 2–YY1 complex." (PMID 37941005, 2023). "Therefore, YY1 plays a crucial role in regulating TME-mediated chemoresistance in tumor cells, which has important implications for diagnosing and treating patients." (PMID 37081988, 2023). "YY1 activates the expression of matrix metalloproteinases (MMPs) (enzymes that degrade the extracellular matrix), facilitating the remodeling of the surrounding tissue and creating the path for tumor cell migration." (PMID 37444616, 2023). "Therefore, targeting YY1 has the potential to inhibit tumor progression and sensitize tumor cells to therapy." (PMID 37444616, 2023). "In the study, YY1 as a member of the PcG protein family can be widely expressed in a variety of tissues and cells and is involved in cell tissue differentiation, chromatin remodeling, and tumor genesis and progression." (PMID 36798788, 2023). "Additionally, the therapeutic values of YY1 inhibition were explored via dCas9 application on tumor growth in vivo." (PMID 37724907, 2023). "This review provides an overview of YY1 biology, its role in tumor development and progression, as well as the strategies explored for YY1-targeted therapy, with a focus on their clinical implications, including those using small molecule inhibitors, RNA interference, and gene editing techniques." (PMID 37444616, 2023).
tumor (continued). "YY1 also contributes to immune evasion by activating the expression of immune checkpoint molecules such as programmed death-ligand 1 (PD-L1), which inhibits the activation of T cells and promotes immune tolerance in tumor cells." (PMID 37444616, 2023). "Additionally, YY1 promotes tumor growth by suppressing the expression of p27 and interacting with it." (PMID 38020889, 2023). "However, there are challenges in developing drugs that specifically target YY1 and delivering them into the tumor." (PMID 37444616, 2023). "YY1 activates the expression of breast cancer-associated gene 1 (BRCA1) and X-ray repair cross-complementing 1 (XRCC1), which repair DNA damage caused by chemotherapy drugs, thereby protecting tumor cells from apoptosis." (PMID 37444616, 2023). "The role of YY1 in cancer is highly dependent on the expression level, and it may act as tumor repressor or oncogene." (PMID 37568827, 2023). "In addition, we observed N‐cad expression via IHC and showed that YY1 knockout reduced N‐cad expression in xenograft tumours." (PMID 37771187, 2023). "Furthermore, a YY1K183R mutant and MOF remarkably antagonized the clone-forming ability of HCT116 and SW480 cells facilitated by YY1, suggesting that the acetylation–ubiquitin mode of YY1 plays an important role in tumor cell proliferation." (PMID 37240065, 2023). "The IHC results of xenograft tumours showed that YY1 staining was reduced by YY1 knockout." (PMID 37771187, 2023). "Therefore, identifying the inhibitors of YY1 is critical for future therapeutic targets that aim to induce the sensitization of tumor cells to cell death and decrease resistance." (PMID 37686541, 2023). "Although YY1 has oncogenic role in cancer, emerging reports suggest that it may also function as a tumor suppressor in certain cancer types." (PMID 37444616, 2023). "It has been reported that YY1 is aberrantly expressed in most tumours, including PCa." (PMID 37771187, 2023). "Therefore, this review focuses on the expression patterns of YY1 in different tumors, its influence on tumor angiogenesis, tumor metabolism and the tumor immune microenvironment, and its potential value in tumor diagnosis and treatment." (PMID 37081988, 2023). "Therefore, developing strategies to overcome these barriers and enhance drug delivery to the tumor site is essential to improve the efficacy of YY1-targeted therapies." (PMID 37444616, 2023). "Consequently, the negative regulation of Fas by YY1 was inhibited, resulting in upregulated Fas expression and tumor cell sensitization to Fas-induced apoptosis." (PMID 37444616, 2023). "We also analyzed how phosphorylation levels of YY1 differed among normal and tumor tissues." (PMID 35791393, 2022). "Depending on the cellular conditions and protein interactions, YY1 may act as a stimulator or suppressor of tumor growth." (PMID 35408813, 2022). "Our findings not only provide novel insights on the regulatory mechanism of ferroptosis, but also elucidate the molecular pathway underlying the tumor suppressive effect of YY2, as well as the antagonistic regulation of tumorigenic potential by the balance between YY1 and YY2." (PMID 35246964, 2022). "This latter observation might be linked to interspecies diversity in terms of regulatory networks occurring between Yy1 and Rkip, and in particular with respect to the specific function of Rkip as tumor suppressor gene in mouse." (PMID 35205667, 2022). "Third, while we identified a connection between YY1 expression and tumor immune cell infiltration, we were unable to determine whether YY1 influences patient survival through immune infiltration." (PMID 35791393, 2022). "Interestingly, as a transcription factor, YY1 exhibits bidirectional transcription regulation in certain tumor contexts." (PMID 35811688, 2022). "Recent findings indicate that therapies directly targeting YY1 or cross talk pathways could improve patients’ outcomes due to the downregulation of PD-L1 expression on tumor cells." (PMID 35719931, 2022).